KDM2B (lysine demethylase 2B)
Diseases named in the same sentence as KDM2B in open-access papers (continued):
Sharing a sentence is not in itself a finding about the gene and the disease.
lung squamous cell carcinoma (1 paper, 2021). "Knockdown of KDM2B inhibited cell proliferation and glycolysis, and induced autophagy in lung squamous cell cancer cells." (PMID 34783291, 2021).
metastatic prostate carcinoma (1 paper, 2024). A carcinoma that arises from the prostate gland and has spread to other anatomic sites. "Since CTCs are the major players in metastasis in the current study, we investigated for the first time the expression of STIM1, ORAI1, and KDM2B simultaneously in Circulating Tumor Cells from the same blood draw of metastatic prostate cancer patients." (PMID 38903530, 2024). "Discussion: STIM1, ORAI1, and KDM2B were overexpressed in CTCs from patients with metastatic prostate cancer." (PMID 38903530, 2024).
myeloid malignancies (1 paper, 2021). "In conclusion, the role of KDM2B in myeloid malignancies appears to be strongly context dependent." (PMID 34944554, 2021).
neuroblastoma (1 paper, 2019). Neuroblastoma (NB) is the most common solid, extracranial childhood tumor. "This is also true for samples from neuroblastoma patients which show an association between levels of KDM2B and poor prognostic." (PMID 30629659, 2019).
non-small cell lung carcinoma (1 paper, 2021). A group of at least three distinct histological types of lung cancer, including non-small cell squamous cell carcinoma, adenocarcinoma, and large cell carcinoma. "On the other hand, KDM2B-mediated demethylation of H3K4me3, along with KDM6A-mediated demethylation of H3K27me3, has been found to promote EZH2 expression and the subsequent progression of non-small cell lung cancer." (PMID 34266408, 2021).
squamous cell carcinoma (1 paper, 2018). A carcinoma arising from squamous epithelial cells. "More KDM genes, including KDM4B, KDM2B, and KDM4A for adenocarcinomas and KDM2B, KDM4C, and KDM4B for squamous cell carcinomas, appear to be associated with patients’ survival." (PMID 29619118, 2018).
T-cell acute lymphoblastic leukemia (1 paper, 2023). Acute lymphoblastic leukemia of T-cell origin. "KDM2B is known to enhance terminally Th17 cell formation and is involved in maintenance of T-cell acute lymphoblastic leukemia, which all could support the role of a phenotypic dysfunctional exhausted T cell type in the clusters without BACH2." (PMID 36879901, 2023).
type 1 diabetes (1 paper, 2021). "KDM2B has been reported to increase glucose metabolism in type 1 diabetes." (PMID 34783291, 2021).
cancer (44 papers, 2012 to 2025). A tumor composed of atypical neoplastic, often pleomorphic cells that invade other tissues. "Finally, E2F4, FOXC1 and KDM2B play oncogenic roles in other types of cancer as well, supporting their identified pathogenic potential in HL." (PMID 34807923, 2021). "All together we would like to propose that the levels of KDM2B could be an important tool for diagnostic, treatment and prognosis of this lethal cancer." (PMID 30629659, 2019). "The expression of KDM2B was first visualized in cytospins of spiked PC-3 and DU-145 cancer cells with PBMCs by immunofluorescence using antibodies for CK, KDM2B, and CD45." (PMID 38903530, 2024). "KDM2B also regulates the self-renewal capacity of cancer and cancer stem cells in hematological and pancreatic cancers." (PMID 39765675, 2024). "In some cancers such as adenocarcinoma and lymphoma, KDM2B is highly expressed and acts as a putative proto-oncogene." (PMID 36975603, 2023). "It was recently revealed that KDM2B expression was increased in different cancer types and acts as an epigenetic regulator in cancer development and progression." (PMID 37033161, 2023). "Studies have shown that KDM2B knockdown can alleviate cytotoxicity and improve cell viability in various cell types, including cancer cells, neurons, and cardiomyocytes." (PMID 37773725, 2023). "KDM2B was mainly positively stained in the nuclei of cancer tissues and was more highly expressed in cancer tissues than in tumor-adjacent normal gastric tissues." (PMID 37033161, 2023). "There are considerable data indicating that the KDM2B protein plays an important role in oncogenesis in a wide range of cancers, through maintenance of stem cell properties, inhibition of differentiation pathways and activation of oncogenic pathways." (PMID 35406676, 2022). "The expression of KDM2B was highly expressed in human cancer cell lines compared with the normal human colon epithelial cell line." (PMID 33791221, 2021). "Further examinations are warranted to clarify how KDM2B selects the specific target genes in cancer cells." (PMID 33779563, 2021). "In pancreatic ductal adenocarcinoma, KDM2B promotes cancer progression through regulating hippo pathway." (PMID 34783291, 2021). "KDM2B promotes cancer cell proliferation and metastasis, cancer stem cell self-renewal, and drug resistance." (PMID 33564100, 2021). "KDM2B can reduce the proliferation of carcinoma cells by inhibiting the expression of oncogenes that play important roles in the self-renewal, differentiation, and apoptosis of stem cells." (PMID 34350210, 2021). "A report showed KDM2B’s expression in primary MEFs and cancer cells is induced by FGF-2 via CREB phosphorylation and activation, downstream of DYRK1A kinase." (PMID 31317506, 2020). "Recently, studies have shown that lysine demethylase 2B (KDM2B) is an important regulator of cancer development and progression." (PMID 31941533, 2020). "It was demonstrated that KDM2B plays critical roles in tumorigenesis and self-renewal of cancer stem cells in hematopoietic malignancies, in gynecological (breast, cervival and ovarian) cancers, and in pancreatic and gastric cancers." (PMID 30629659, 2019). "We cannot discard the possibility that KDM2B blocks ERK activation as was described in others model of undifferentiated cells like cancer cells." (PMID 30629659, 2019). "So far, KDM2B has been involved in mechanisms, independently or interactively with microRNAs, for cancers of the blood, pancreas, breast, or stomach." (PMID 29619118, 2018). "In vertebrates, the KDM2 subfamily of KDMs consists of KDM2A and KDM2B; studies in the past decade have linked mutations of these KDM2 paralogs to a number of human cancers." (PMID 30233643, 2018). "The histone demethylase KDM2B is known to play important roles in tumorigenesis and self-renewal of cancer stem cells (66, –, 68)." (PMID 30135119, 2018).
cancer (continued). "Genetic alterations in JmjCs, including KDM2A, KDM2B, KDM4A, KDM4B, KDM42C and KDM5B, have all been linked to cancer progression and these enzymes have been suggested as chemotherapeutic targets." (PMID 25145438, 2014). "KDM2B is a novel oncogene, and it is upregulated in a wide range of cancers." (PMID 38903530, 2024). "Many studies indicate that KDM2B has dual effects in cancer development." (PMID 36975603, 2023). "Furthermore, a lot of evidences have revealed that histone modifying enzymes such as KDM2B are involved in the initiation and progression of human cancer." (PMID 33779563, 2021). "In summary, we found that hiBiv-associated promoters are more susceptible to hypermethylation in cancer, and that unlike deletion of non-canonical Kdm2b in mESC, deletion of canonical PRC components was associated with CGI shore hypermethylation." (PMID 32131813, 2020). "Taken together, these results indicated that acetylation of KDM2B promoted cancer cells growth." (PMID 31218831, 2019). "Thus, the role of KDM2A and KDM2B in tumorigenesis seems to be dependent on different types of cancers." (PMID 30233643, 2018). "Similarly to KDM2A, KDM2B removes H3K36me2 and can contribute to cellular immortalization, transformative capacity in cancer and reprogramming." (PMID 23697932, 2013). "Among the most important histone demethylases associated with the development of cancer are LSD-1/KDM1A, and members of the Jumonji family JARID1A-1C/KDM5A-5C, JHDM1B/KDM2B, JMJD2C/KDM4C, JMJD2A/KDM4A, JMJD3/KDM6B, and UTX/KDM6A, which will be analyzed in detail in the following paragraphs." (PMID 24280700, 2012). "Further, we analysed whether KDM2B acetylation promoted the migration of cancer cells." (PMID 31218831, 2019). "The two other identified genes (KDM2B and KCTD11) were found to be involved with neurodevelopmental disorders and cancer, respectively." (PMID 40349045, 2025). "Alternatively, KDM2B hinders ribosomal RNA genes, MYC protein, and induces c-Fos ubiquitylation, leading to reduced cancer cell proliferation." (PMID 36975603, 2023). "BCOR is likely to be a crucial mediator of BCL6 function in these cancers, whereas BCL6 can coordinate the actions of the BCOR polycomb-like complex (BCOR, PCGF1, RING1B, and KDM2B) to potently repress target genes." (PMID 33468080, 2021). "We noticed that genes encoding chromatin modifiers were often hypermethylated in several cancer types, including the histone methyltransferases KMT2C (11 cancer types) and NSD1 (7 cancer types) and the histone demethylase KDM2B (6 cancer types)." (PMID 34871444, 2021). "KDM2B has been previously shown to be nuclear factor (NF)-κB dependent, and be negatively regulated by TRAIL treatment in several cancer cell lines." (PMID 28304334, 2017). "Therefore, our data may enrich the mechanism of the KDM2B's regulatory role in various cancers." (PMID 26989077, 2016). "As well as being overexpressed in certain cancers, KDM2A and KDM2B have also been found to be down-regulated in prostate cancer and glioblastoma respectively." (PMID 25145438, 2014). "Among them, KDM2B expression was strongly and highly significantly correlated with sensitivity to the HDAC inhibitor vorinostat in the NCI-60 cancer cell lines (Pearson r = -0.51, p = 4.3 × 10–5), providing a strong support for our initial finding of this association in the CCLE-GDSC dataset." (PMID 33676569, 2021). "Although studies have demonstrated that KMD2B regulates cancer stemness, the expression roles and regulatory mechanism of KDM2B in CR-CSCs have not been studied." (PMID 33791221, 2021). "We observed KDM2B mainly positive staining in the nucleus of cancer tissues, but negative or weak expression in the adjacent normal tissues." (PMID 31941533, 2020). "KDM2B silencing is also reported to increase levels of tumor‐suppressing miRNA let‐7b, thereby downregulating EZH2 and reducing the entry into S‐phase and thus cancer growth." (PMID 29360266, 2018).
tumor (42 papers, 2012 to 2026). "Long-term analysis of tumor growth for 30 days with noninvasive bioluminescence imaging revealed that loss of KDM2B also attenuates tumor growth in vivo." (PMID 28661478, 2017). "To examine the effects of KDM2B loss on tumor growth in vivo, we generated shControl and shKDM2B cells expressing both firefly luciferase (Fluc) and mCherry." (PMID 28661478, 2017). "Loss of KDM2B also suppressed antiapoptotic genes and inhibited tumor growth in vivo." (PMID 39765675, 2024). "As well as KDM2A and KDM2B, which have K3K36me2 and H3K4me3 as their substrate, where its deregulation is associated with increased proliferation of stem cells and tumor growth and metastasis among other processes such as cell proliferation and drug resistance, among others." (PMID 35480330, 2022). "Furthermore, the increased expression of KDM2B was positively associated with poorer tumor differentiation, lymph nodes metastasis and higher TNM stages (P = 0.001)." (PMID 31941533, 2020). "Besides, EZH2 expression was also positively correlated with KDM2B, which was significantly associated with tumor histological type, stage, and lymph node metastasis." (PMID 33163485, 2020). "However, KDM2A appears to play a tumor suppressive role in colon cancer, and similarly, KDM2B is implicated to play a tumor suppressor role in lymphoma and brain cancer." (PMID 30233643, 2018). "This suggests that while short-term loss of KDM2B can alter the epigenetic landscape of tumor cells in favor of apoptosis, long-term consequences of the epigenome alterations can reduce proliferation and be detrimental without additional external apoptotic stimuli." (PMID 28661478, 2017). "Among the primary tumor samples, AKAP9, KDM2B, MAGED1, MKI67, PCLO, and TRAF1 mutations were identified." (PMID 41614915, 2026). "Among the 95 primary tumor samples, AKAP9, KDM2B, MAGED1, MKI67, PCLO, and TRAF1 mutations were identified as single-occurrence events and were absent in the metastatic samples." (PMID 41614915, 2026). "In PC, inducing KDM2B protein expression has been shown to promote tumor progression through interaction with Polycomb group proteins to repress developmental genes." (PMID 39239542, 2024). "KDM2B is involved in numerous pathological processes, for instance, cell senescence and tumor development." (PMID 37773725, 2023). "Histone‐modifying lysine‐specific demethylase 2B (KDM2B) is involved in numerous pathological processes, such as cell senescence and tumor development." (PMID 37773725, 2023). "KDM2B has been shown to be involved in a variety of fundamental biological and pathological processes, such as cell cycle, senescence, and tumor development." (PMID 37773725, 2023). "Recently, we found that canine HSA highly expressed three histone demethylases (KDM1A, KDM2A and KDM2B) out of which KDM2B was necessary for HSA cell survival by positively regulating the DNA damage response system in tumor cells." (PMID 35136176, 2022). "Our results showed that KDM2B knockdown led to a significant reduction in the tumor volume in mice transfected with si-KDM2B." (PMID 34783291, 2021). "In several model systems KDM2B acts as a tumor suppressor, by preventing degradation of a second tumor-suppressor, by inhibiting tumor-suppressor antagonists, or by reducing cell activation." (PMID 34944554, 2021). "The expression of KDM2B was reduced by si-KDM2B in tumor tissues, indicating the efficiency of si-KDM2B in depleting KDM2B." (PMID 34783291, 2021). "Pancreatic cancers with increased KDM2B promoted tumor formation in cooperation with the oncogene Kras in an in vivo model." (PMID 34220955, 2021). "Overexpression of KDM2B is observed in ovarian cancer and when knocked down in vitro and in vivo reduced cell proliferation, migration and tumor growth." (PMID 34220955, 2021). "Next, we sought to investigate the effect of KDM2B silencing on tumor size in xenograft tumor model." (PMID 34783291, 2021).
tumor (continued). "Our result showed that the average expression of KDM2B in tumor tissues that are in stages I–II and stage II was higher than that of stages II–III + III." (PMID 33791221, 2021). "Analysis of expression data obtained from TCGA database showed that KDM2B was upregulated in primary tumor tissues." (PMID 34783291, 2021). "We first measured the expression of KDM2B in CRC by IHC analysis using TMA that included 75 tumor tissues (grades I–IV) and 75 normal tissues." (PMID 33791221, 2021). "A decrease in Ki67 and phosphorylated AKT was also observed in tumor tissues transfected with si-KDM2B." (PMID 34783291, 2021). "A previous study reported that the downregulation of KDM2B inhibits cell proliferation and affects the progression of the cell cycle in tumor cells including HeLa cells." (PMID 33791221, 2021). "KDM2B has been considered as either a tumor suppressor or ontogenesis depending on the cellular context." (PMID 33791221, 2021). "Future studies exploring any potential therapeutic targeting of KDM2B will need to consider that KDM2B either acts as an oncogene or a tumor suppressor depending on the specific genetic background." (PMID 34944554, 2021). "The effects of KDM2B acetylation on the transcription of target genes, as well as tumour growth and metastasis were then studied." (PMID 31218831, 2019). "Chromatin immunoprecipitation was carried out to test the effects of KDM2B acetylation on the transcription of its target genes, like p21 and puma. p21 and puma are the two key genes in regulating tumour cells growth as well." (PMID 31218831, 2019). "Further, KDM2B inhibition sensitizes this highly resistant tumor to chemotherapy, suggesting a potential clinical paradigm combined with standard therapies." (PMID 29360266, 2018). "To exclude the possibility that elevated KDM2B expression was a cell culture artifact, we performed qRT/PCR and immunoblot analysis on total RNA and protein isolated directly from primary tumor tissue biopsies." (PMID 29360266, 2018). "As such, the mammalian lysine-specific demethylase 2 (KDM2) homologs, KDM2A and KDM2B, are either oncogenic or tumor suppressive depending on specific pathological contexts." (PMID 30233643, 2018). "Moreover, primary tumor samples had exclusive mutations in AKAP9, KDM2B, MAGED1, MKI67, PCLO, and TRAF1." (PMID 41614915, 2026). "Similarly, NDY1/KDM2B, a histone H3K36me2, H3K36me1, and H3K4me3 demethylase, is upregulated in the primary tumor environment driven by bFGF signals." (PMID 37048074, 2023). "ISOS-1 tumor cells in Balb/c mice also expressed KDM2B as high as in canine HSA." (PMID 35136176, 2022). "Abnormal regulation of DNA replication coupled processes could be linked to tumorigenesis, as shown by the tumor suppressive role of BCOR and the paradoxical roles of KDM2B in prevention or promotion of malignant transformation of HSPCs31–34,56,57." (PMID 36443290, 2022). "From stage I to stage III in CRC, the expression of KDM2B was higher in tumor tissues than that of the corresponding adjacent-normal tissues in each stage, and this difference exhibited an important significance in stages I–II and stage II than stage II–III + III." (PMID 33791221, 2021). "Contradictory findings, however, support a tumor-suppressor role for KDM2B in myeloid malignancies." (PMID 34944554, 2021). "Knockdown of KDM2B repressed the tumor growth in xenograft tumor model." (PMID 34783291, 2021). "Further experiment found that knockdown of KDM2B inhibited tumor growth in mouse model." (PMID 34783291, 2021). "Knockdown of KDM2B inhibits cell proliferation in vitro and tumor growth in vivo in LUSC." (PMID 34783291, 2021). "We found that the expression of KDM2B increased in tumor tissues compared with normal tissues." (PMID 33791221, 2021).